CCDC8 (coiled-coil domain containing 8 subunit of 3M complex)
Description:
Core component of the 3M complex, a complex required to regulate microtubule dynamics and genome integrity. It is unclear how the 3M complex regulates microtubules, it could act by controlling the level of a microtubule stabilizer. Required for localization of CUL7 to the centrosome.
Synonyms: DKFZp564K0322; 3M3; PPP1R20; p90
Tractability: Antibody: its Gene Ontology location is reachable by antibodies, with high confidence; the Human Protein Atlas places it where antibodies can reach.
Gene: Protein-coding gene on chromosome 19 (46,410,329 to 46,413,564, reverse strand). Ensembl gene ENSG00000169515.
Subcellular location: Cytoplasm; Cytoplasm, cytoskeleton, microtubule organizing center, centrosome
Subcellular location (Human Protein Atlas): Cytosol; Plasma membrane; Nucleoplasm
Pathways (Reactome):
Metabolism of proteins: Neddylation
Gene Ontology:
Molecular function: protein binding
Biological process: microtubule cytoskeleton organization; regulation of mitotic nuclear division
Cellular component: 3M complex; centrosome; cytoplasm; plasma membrane; cytosol
Genetic constraint (gnomAD): Loss-of-function variants: 7 observed, 6.59 expected, observed/expected ratio (o/e) 1.06, 90% interval 0.6 to 1.8. That is too few expected variants to judge how well the gene tolerates losing a copy. Missense variants: 724 observed, 714.74 expected, observed/expected ratio (o/e) 1.01, 90% interval 0.95 to 1.08. Synonymous variants: 310 observed, 288.06 expected, observed/expected ratio (o/e) 1.08, 90% interval 0.98 to 1.18.
Homologues: Orthologues: chimpanzee CCDC8 (95% identical), macaque CCDC8 (86% identical), dog CCDC8 (73% identical), pig CCDC8 (67% identical), mouse Ccdc8 (65% identical), rat Ccdc8 (65% identical), rabbit CCDC8 (64% identical). Paralogues in human: PNMA6F (14% identical), PNMA6E (13% identical), PNMA3 (12% identical), PNMA6A (12% identical), PNMA2 (12% identical), PNMA1 (12% identical), PNMA5 (10% identical), MOAP1 (9% identical), ZCCHC12 (9% identical), ZCCHC18 (9% identical), PNMA8A (8% identical), PNMA8B (7% identical), and 1 more.
Diseases named in the same sentence as CCDC8 in open-access papers:
CCDC8 is named in the same sentence as 23 diseases in open-access papers, as found by Europe PMC text mining. Sharing a sentence is not in itself a finding about the gene and the disease. The quoted sentences say what the papers report.
3-M syndrome (14 papers, 2014 to 2025). 3M syndrome is a primordial growth disorder characterized by low birth weight, reduced birth length, severe postnatal growth restriction, a spectrum of minor anomalies (including facial dysmorphism) and normal intelligence. "With the development of gene diagnosis technology, variants in the CUL7, OBSL1, and CCDC8 genes have been identified as responsible for 3M syndrome." (PMID 37719700, 2023). "Genetically confirmed patients with 3M syndrome carry mutations in CCDC8 (5%), OBSL1 (25%) or CUL7 (70%)." (PMID 32235515, 2020). "Mutations in CUL7, OBSL1 and CCDC8, leading to disordered ubiquitination, cause one of the commonest primordial growth disorders, 3-M syndrome." (PMID 24711643, 2014). "In humans, the mutation in the 19q13.32 region of CCDC8 is associated with 3M syndrome dwarfism, a rare inherited disorder characterized by low body weight and short length at birth, short stature as adults, widespread skeletal abnormalities, and unusual facial features." (PMID 37238140, 2023). "CCDC8 encodes microtubule regulatory proteins and stabilized proteins that cause 3-M syndrome." (PMID 36350824, 2022). "Also, CUL7–RBX1 binds OBSL1 and CCDC8 in a complex named ‘3M’ in reference to mutations in the CUL7, OBSL1 or CCDC8 genes causing 3M syndrome." (PMID 35982156, 2022). "While CUL7 and OBSL1 account for ~94% of known 3-M syndrome cases, the remaining 6% (at least partly accounted for by CCDC8 mutations) of undiagnosed cases suggests that additional genes and perhaps regulatory (non-coding) mutations in known genes are yet to be implicated." (PMID 25923536, 2015). "CCDC8 encodes a coiled-coil domain containing protein (CCDC8) that is one of three proteins that are mutated in patients with 3 M syndrome, an autosomal recessive disorder characterised by short stature, skeletal abnormalities, reduced male hormone and blood vessel bulges." (PMID 26052355, 2015). "Since the reported role of CCDC8 mutations in 3-M syndrome links it to Obsl1 and E3 ligase Cul7, we tested whether Obsl1 or Cul7 could also inhibit HIV-1 production." (PMID 26423533, 2015). "CUL7 mutations account for 70% of 3M syndrome cases, with the remainder caused by mutations in OBSL1 and CCDC8 occurring in a mutually exclusively manner between these three genes." (PMID 35982156, 2022). "They noted that, in terms of the clinical and biochemical 3M syndrome phenotype, children with CUL7 mutations were significantly shorter than those with OBSL1 or CCDC8 mutations." (PMID 32235515, 2020). "The 3M syndrome is caused by loss-of-function mutations in the genes encoding cullin 7 (CUL7), obscurin-like 1 (OBSL1), and coiled-coil domain containing protein 8 (CCDC8)." (PMID 27796265, 2017). "Our previously published transcriptomic data from 3-M syndrome patients with null mutations in either CUL7, OBSL1 or CCDC8 revealed that IGF2 expression is significantly reduced." (PMID 24711643, 2014). "In this study, we have used proteomic and transcriptomic approaches to identify the putative interacting partners of CUL7, OBSL1 and CCDC8 to create a 3-M syndrome interactome." (PMID 24711643, 2014). "The diagnosis of 3M syndrome could be confirmed by identifying biallelic variants in CUL7, OBSL1, or CCDC8." (PMID 37877343, 2023). "3‐M syndrome is classified into types I, II, and III, which have been identified to be associated with the exclusive variants in cullin 7 (CUL7; MIM *609577), obscurin‐like 1 (OBSL1; MIM *610991), and coiled‐coil domain‐containing protein 8 (CCDC8; MIM *614145) genes, respectively." (PMID 32141654, 2020). "The prevalence of 3M syndrome has not yet been clearly defined, but pathogenic variants of three genes, namely, CUL7 (3M1, MIM #273750), OBSL1 (3M2, MIM #612921), and CCDC8 (3M3, MIM #614205), were responsible for 77.5%, 16%, and <5% of 3M syndrome cases, respectively." (PMID 37877343, 2023).
breast carcinoma (5 papers, 2015 to 2024). "Previous studies identified that dysregulation of CCDC8 was associated with various cancers such as breast cancer, gastric cancer, and lung cancer." (PMID 34569727, 2021). "Forty-eight hours after initial transfection with siRNA oligos against BNC1, CCDC8 or GALNT9 breast cancer cell lines showed loss of specific gene expression." (PMID 26052355, 2015). "Previous studies have suggested CCDC8 (coiled-coil domain containing 8) was frequently epigenetically dysregulated in renal cell carcinoma and in breast carcinomas that metastasis to the brain." (PMID 30886542, 2019). "Breast cancer brain metastases upregulate KRT13 and downregulate CCDC8, and these genes were differentially expressed in the primary and metastatic samples." (PMID 37138793, 2023).
breast tumor (3 papers, 2015 to 2020). "Promoter methylation of BNC1 (17 %) and CCDC8 (40 %) in primary breast tumours was infrequent (≤45 %), and statistically significantly lower than that of the frequency of methylation in BBM (p = 0.0001 and 0.01, respectively)." (PMID 26052355, 2015). "This common CCDC8 methylation in primary breast tumour and resulting brain metastasis was confirmed by sequencing individual alleles for pairs of tumours from two patients (patient 11 and 15 (BM11, Primary BT 11 and BM15, Primary BT 15))." (PMID 26052355, 2015). "However, the CCDC8 promoter was commonly methylated in primary breast tumours that eventually develop brain metastases and as such it can be categorised as an early event in tumour evolution/metastasis." (PMID 26052355, 2015). "Our findings indicate that epigenetic dysregulation of GALNT9, CCDC8 or BNC1 in breast tumours may contribute to metastasis to the brain and possibly other distant organs." (PMID 26052355, 2015). "We have identified three genes, GALNT9, CCDC8 and BNC1, that were frequently methylated (55, 73 and 71 %, respectively) and silenced in BBM and infrequently methylated in primary breast tumours." (PMID 26052355, 2015). "Both early and late methylation events will appear similarly in our initial analysis; the genes will be frequently methylated in BBM and infrequently methylated in unrelated primary breast tumours, this is the case for BNC1, CCDC8 and GALNT9." (PMID 26052355, 2015). "This analysis has identified three genes (BNC1, CCDC8 and GALNT9) that are differentially methylated in primary breast tumours and BBM." (PMID 26052355, 2015). "From our broad-ranging screens, we have identified GALNT9, BNC1 and CCDC8 as frequently methylated in BBM and significantly less frequently methylated in primary breast tumours." (PMID 26052355, 2015). "However, it is worth noting that to our knowledge this is the first time that promoter methylation in CCDC8, HOXD3, PCDH8, PENK, STAT3, SFRP2 and WIFI has been described in primary breast tumours." (PMID 26052355, 2015). "CCDC8 was commonly methylated in brain metastases and their associated primary tumours whereas GALNT9 and BNC1 were methylated and silenced only in brain metastases, but not in the associated primary breast tumours from individual patients." (PMID 26052355, 2015).
growth disorder (2 papers, 2015 to 2019). "It is thought that 3M-growth syndrome is caused by a deficiency in protein turnover due to the finding that a majority of patients with 3M-growth disorder display mutations in cullin-7, Obsl1, and Ccdc8." (PMID 31098411, 2019).
lung carcinoma (2 papers, 2021 to 2024). "CCDC8 and CCDC65 have been reported to act as tumor suppressors in tumors such as gastric and lung cancer." (PMID 39261464, 2024).
renal carcinoma (2 papers, 2021 to 2025). A carcinoma arising from the epithelium of the renal parenchyma or the renal pelvis. "According to HPA, CCDC8 is a favorable prognostic marker in renal cancer, which is consistent with our prediction." (PMID 34569727, 2021). "Finally, we identify early dysregulated genes (e.g., FBP1, CCDC8, ECHS1, CLDN7) and pathways in renal cancer, often related to metabolism (e.g., pentose phosphate pathway)." (PMID 41188181, 2025).
Bladder Cancer (1 paper, 2025). "In high CCDC8 expression bladder cancer, the lower frequency of FGFR3 mutations aligns with their more aggressive phenotype." (PMID 39744495, 2025). "The mutational landscape of bladder cancer samples was analyzed to compare the genetic alterations between the CCDC8 high group and the CCDC8 low group." (PMID 39744495, 2025). "CCDC8 expression levels in bladder cancer are significantly associated with the mutation frequencies of various genes, notably FGFR3 and KDM6A." (PMID 39744495, 2025). "Our findings extend these observations to bladder cancer, showing that high CCDC8 expression is linked to poor prognosis and a reduced response to immunotherapy." (PMID 39744495, 2025). "While our study identifies CCDC8 as a significant prognostic marker and promising therapeutic target in bladder cancer, further research is necessary to address our limitations and translate these findings into clinical practice." (PMID 39744495, 2025). "The significant link between CCDC8 and the immune microenvironment in bladder cancer highlights the importance of understanding immune modulation in cancer therapy." (PMID 39744495, 2025). "Given its crucial role in other malignancies, investigating potential implications of CCDC8 in bladder cancer is imperative." (PMID 39744495, 2025). "Our study seeks to elucidate the prognostic significance of CCDC8 in bladder cancer by examining its expression patterns, immunological effects in the tumor immune environment, and molecular landscape." (PMID 39744495, 2025). "Our findings indicated that CCDC8 was significantly downregulated in 17 tumor types, including bladder cancer (BLCA), and upregulated in only 2 cancer types, specifically head and neck squamous cell carcinoma (HNSC) and cholangiocarcinoma (CHOL)." (PMID 39744495, 2025). "In bladder cancer (BLCA), the mutation frequency of CCDC8 was 0.5%, with missense mutations being the predominant type." (PMID 39744495, 2025). "In cohort 1, we analyzed the correlation between CCDC8 expression level and the bladder cancer molecular subtypes." (PMID 39744495, 2025). "We performed bioinformatics analysis and immunohistochemistry to investigate the biological landscape of CCDC8 in various tumors, with a particular focus on bladder cancer." (PMID 39744495, 2025). "The identification of CCDC8 as a prognostic marker in bladder cancer is consistent with its known role in other cancers." (PMID 39744495, 2025). "Future research should focus on validating these results and exploring the mechanistic role of CCDC8 in modulating treatment responses, aiming to develop more personalized and effective therapeutic strategies for bladder cancer." (PMID 39744495, 2025). "We observed that high CCDC8 expression correlates with poor prognosis and a suboptimal response to immunotherapy in bladder cancer." (PMID 39744495, 2025). "Our study establishes CCDC8 as a key player in bladder cancer progression and immune regulation." (PMID 39744495, 2025). "Further investigation into the mechanistic roles of CCDC8 could provide valuable insights for developing targeted therapies and improving prognostic results for bladder cancer patients." (PMID 39744495, 2025). "Comprehensive characterization of CCDC8 was applied to prognostic prediction in bladder cancer, indicating that targeting CCDC8 may be a potential therapeutic strategy." (PMID 39744495, 2025). "Notably, the results for bladder cancer (BLCA) demonstrated significant statistical relevance, indicating that high CCDC8 expression levels may serve as an independent predictor of poor prognosis in BLCA patients." (PMID 39744495, 2025).
brain tumours (1 paper, 2015). "We analysed the methylation status BNC1, CCDC8 and GALNT9 in metastatic brain tumours and corresponding primary tumours from individual patients." (PMID 26052355, 2015). "Total RNA was extracted from 15 metastatic brain tumours to determine the expression of BNC1, CCDC8 and GALNT9 by RT-PCR." (PMID 26052355, 2015).
intrauterine growth restriction (1 paper, 2023). "Deletion of CCDC8 caused perinatal lethality, intrauterine growth restriction, and placental defects." (PMID 37238140, 2023).
metabolic syndrome (1 paper, 2018). A cluster of metabolic risk factors for CARDIOVASCULAR DISEASES and TYPE 2 DIABETES MELLITUS. "The top differentially methylated CpG island associated with metabolic syndrome in males was found in the coiled-coil domain containing 8 (CCDC8) gene, although this finding was not replicated in our validation sample." (PMID 29850476, 2018). "Other sites may have stronger associations with metabolic syndrome, or in the case of the CCDC8 gene which was not validated, other areas of the gene may have stronger associations with metabolic syndrome." (PMID 29850476, 2018).
metastatic tumours (1 paper, 2015). "This suggests differing roles for these genes in the evolution of metastatic tumours; CCDC8 methylation occurs at an early stage of metastatic evolution whereas methylation of GANLT9 and BNC1 occurs at a later stage of tumour evolution." (PMID 26052355, 2015).
uterine corpus endometrial carcinoma (1 paper, 2025). A endometrial carcinoma (disease) that involves the body of uterus. "For instance, uterine corpus endometrial carcinoma (UCEC) exhibited the highest mutation frequency of CCDC8, whereas other cancer types showed relatively lower frequencies." (PMID 39744495, 2025).
viral infections (1 paper, 2015). "Therefore, CCDC8 is a very important factor relevant to cell growth, apoptosis, and probable anti-viral infections, although its exact functions are unknown." (PMID 26423533, 2015).
tumor (7 papers, 2012 to 2025). "Dysregulation of CCDC8 occurs in the early stage of BRCA progression and is associated with tumor metastasis to the brain and other organs." (PMID 38235137, 2023). "During tumor evolution, CCDC8 dysregulation early occurs, which has the potential to be utilized as a prognostic marker in addition to being a potential therapeutic target." (PMID 33005105, 2020). "In contrast, out of 11 matched pairs, CCDC8 was commonly methylated in 10 corresponding primary tumours." (PMID 26052355, 2015). "CCDC8 dysregulation occurs early during tumour evolution, in addition to being a potential therapeutic target this early inactivation has the potential to be utilised as a prognostic biomarker." (PMID 26052355, 2015). "In contrast, CCDC8 promoter methylation is detectable in most primary tumours that metastasise to the brain, suggesting that it may play an important role in the early stages of primary tumour metastasis." (PMID 26052355, 2015). "BNC1, CCDC8 and GALNT9 were frequently downregulated or silenced in these tumours and reduced expression correlated to promoter methylation as determined by CoBRA and base-resolution sequencing." (PMID 26052355, 2015). "We have identified that CCDC8 is dysregulated at an early point of BBM, and its promoter methylation is detectable in the primary tumours that proceed to metastases." (PMID 26052355, 2015). "The results showed downregulation of HOXD3, PRUNE2, CD302, CCDC8, and KLF2 (tumor vs. control)." (PMID 41186818, 2025). "The low frequency of methylation in primary tumours indicates that BNC1 and CCDC8 may contribute to BBM and are good candidates for further investigation." (PMID 26052355, 2015). "To ensure that CoBRA digests were representative of high methylation status in tumours, we carried out base-resolution analysis of promoter region methylation for BNC1, CCDC8 and GALNT9 by cloning and sequencing individual bisulfite-modified alleles from select tumours." (PMID 26052355, 2015).
cancer (3 papers, 2021 to 2025). A tumor composed of atypical neoplastic, often pleomorphic cells that invade other tissues. "There were significant differences in the mutation frequency and types of CCDC8 among different cancers." (PMID 39744495, 2025). "Moreover, we investigated the mutation characteristics of CCDC8 across various cancer types, focusing on mutation frequency and types." (PMID 39744495, 2025). "We initially examined the expression levels of CCDC8 in normal and tumor samples across 34 different cancer types using data from TCGA." (PMID 39744495, 2025). "The results indicate that CCDC8 expression is significantly higher in females and in advanced cancer stages (III/IV)." (PMID 39744495, 2025). "Next, the relationship between CCDC8 and immune checkpoint genes in a pan-cancer context was analyzed." (PMID 39744495, 2025). "Subsequently, we assessed the prognostic value of CCDC8 in TCGA pan-cancer datasets using univariate Cox regression analysis." (PMID 39744495, 2025). "Overall, the identification of CCDC8 as a predictive marker for immunotherapy highlights its importance in enhancing personalized treatment approaches in cancer therapy." (PMID 39744495, 2025).
CCDC8 also shares sentences with these, for which no sentence is quoted: cholangiocarcinoma (1 paper); cleft lip (1); dwarfism (1); gastric cancer (1); head and neck squamous cell carcinoma (1); hypospadias (1); ovarian carcinoma (1); psychiatric diseases (1).